RNU6-692P (RNA, U6 small nuclear 692, pseudogene)
Gene: Small nuclear RNA gene on chromosome 2 (147,408,342 to 147,408,448, forward strand). Ensembl gene ENSG00000207225.
Homologues: Orthologues: chimpanzee U6 (99% identical), macaque U6 (94% identical), mouse Gm26181 (71% identical), rat LOC120097661 (67% identical). Paralogues in human: RNU6-1152P (89% identical), RNU6-41P (88% identical), RNU6-820P (88% identical), RNU6-106P (87% identical), RNU6-1181P (87% identical), RNU6-211P (87% identical), RNU6-35P (87% identical), RNU6-434P (87% identical), RNU6-10P (86% identical), RNU6-12P (86% identical), RNU6-13P (86% identical), RNU6-16P (86% identical), and 1287 more.